TOP2A (DNA topoisomerase II alpha)
Diseases named in the same sentence as TOP2A in open-access papers (continued):
Sharing a sentence is not in itself a finding about the gene and the disease.
tumor (continued). "However, not all tumours with high TOP2A expression are sensitive to pirarubicin treatment." (PMID 35711974, 2022). "We suppose that TOP2A may not be related (at least not by itself) to early stages of carcinogenesis and morphological undifferentiating, which may result in further aggressive tumor biological behavior." (PMID 23398928, 2013). "Also, we show that TOP2A gene copy number alterations are not observed in this type of tumor." (PMID 23398928, 2013). "The TOP2A gene was also highly overexpressed in TCGA TNBC samples (12 normal breast tissues and 137 tumor samples of the TNBC patients) with limited expression in normal mammary tissues." (PMID 37880313, 2023). "Subclustering analysis of the tumor, myoepithelial, and macrophage populations identified proliferative (TOP2A +), SCD +, and S100A8+ tumor cells, although these populations were not spatially distinct." (PMID 38114474, 2023). "Patients TN5, 7 and 11 revealed no signs of HER2/TOP2A allelic imbalance, IHC scores were 0–1+, SISH yielded ratios of 1.1–1.6 and the samples contained 30–95 % tumor cells." (PMID 26022247, 2015). "As TOP2A gene amplification is extremely rare (and not detected at all in some studies), we did not test immunohistochemically HER2-negative tumours for TOP2A gene amplification." (PMID 17088909, 2006). "The tumor microenvironment analysis revealed that TOP2A expression was negatively correlated with the Stromal score and ESTIMATE score, while there was no statistical significance between TOP2A expression and the Immune score." (PMID 37980167, 2023). "The relative expression levels of CDKN3, MKI67, CEP55, SPAG5, AURKA, TOP2A were consistent with the results of bioinformatics analysis (P < 0.05), while the expression levels of UBE2C, CHEK1 and BIRC5 in tumor samples were not significantly different from adjacent normal samples." (PMID 35178291, 2022). "Overall, 28 out of 43 patients (65%) whose tumours lacked a genomic match to a clinical trial were eligible for investigational drugs as a result of TMP analysis (PTEN, EGFR, HER2, GPNMB, MSLN, TROP2, TOPO1 or TOP2A as emerging positive predictive markers)." (PMID 31537838, 2019). "The negative relationship between TOP2A expression and M1 macrophages’ infiltration level in TGCT and THYM suggests that high TOP2A expression may inhibit the function of M1 macrophages to promote the tumor progression." (PMID 35778520, 2022). "Previous study shows that tumor cells were sensitive to TOP2A poisons without initiating compensatory expression of TOP2A when TOP1 was suppressed, indicating that increased response to etoposide may be independent to TOP2A expression." (PMID 24103454, 2013).
infection (21 papers, 2014 to 2026). The state of being infected such as from the introduction of a foreign agent such as serum, vaccine, antigenic substance or organism. "To identify infection-specific partners, we performed GFP pull downs on infected cells expressing GFP-tagged TOP2A or TOP2B CTDs with mutated NLS, as these proteins are recruited to viral factories, but not nuclear DNA." (PMID 40557872, 2025). "At 7 h post infection, TOP2A was located both, in the nucleus and at the viral factories, while TOP2B was completely recruited to viral factories." (PMID 40557872, 2025). "ASPM and TOP2A were significantly overexpressed at 24 h post-infection in SCs demonstrated by western-blotting." (PMID 37478057, 2023). "Four genes (ASPM, CENPF, MKI67, and TOP2A), which are well documented as stem cell and cell proliferation markers, were overexpressed at 24 h post-infection." (PMID 37478057, 2023). "We demonstrated that T cells derived from patients with chronic viral (HBV, HCV, and HIV) infection had lower Top2α protein levels and enzymatic activity, along with an accumulation of the Top2α cleavage complex (Top2cc) in genomic DNA." (PMID 32193368, 2020). "The loss of TOP2B but not TOP2A also resulted in a decrease in dsRNA formation during infection, which is consistent with a reduction in AVG formation." (PMID 40557872, 2025). "Although the presence of TOP2A and TOP2B on cytosolic viral factories has been established, their specific roles during vaccinia replication and infection remain unexplored." (PMID 40557872, 2025). "Our analysis reveals that vaccinia redirects TOP2A and TOP2B to cytosolic sites of viral replication early during infection in a two-step process." (PMID 40557872, 2025). "As an initial approach to explore the role of Top2α in DNA damage and T cell apoptosis, we examined the levels of Top2α in CD4 T cells derived from individuals with chronic viral (HCV, HBV, HIV) infections." (PMID 32193368, 2020). "Since the progression of infection depends on the cell cycle, we also probed mRNA levels for the cell cycle markers GMNN and TOP2A introduced in the previous sections." (PMID 31653857, 2019). "We hypothesize that targets identified in our iPOND analysis, such as GINS3, TOP2A and XRCC1, may play a role in maintaining host replisome stability as wtAAV2 mono-infection progresses long-term." (PMID 40825038, 2025). "Host proteins enriched at cellular replication forks during infection included DNA processing factors such as GINS, TOP2A, PRIM1/2, RPA2 and XRCC1; DDR signaling proteins such as CSNK2A1/3; cell cycle regulator proteins such as TFDP2 and SFN1; as expected for cells undergoing replication stress." (PMID 40825038, 2025). "In contrast, RNAs related to checkpoint signaling (e.g., CDK5RAP3 and CDC5L) and meiotic cell cycle (e.g., TOP2A) were decreased in the cells infected by Salmonella compared to cells without infection under the aerobic condition." (PMID 37040488, 2023).
adenocarcinoma (11 papers, 2013 to 2023). A common cancer characterized by the presence of malignant glandular cells. "Previously, a correlation with positive staining for TOP2A was identified in male adenocarcinoma patients." (PMID 24649266, 2013). "Since TOP2A amplification is a marker of sensitivity to anthracyclines, smoking male patients with adenocarcinoma are likely to benefit from anthracycline treatment." (PMID 24649266, 2013). "However, quantitative differences in the expression of Tk1, Top2a, Hmgb2, Rrm2, Kpna2, and H1fx were observed and were found to be strongly up-regulated in small-sized adenocarcinomas." (PMID 27602772, 2016). "INS, TOP2A, ACACA, ALB, and TXN are the key genes which play an important role in adenocarcinoma." (PMID 30425814, 2018). "Furthermore, TOP2A expression was positively correlated with histological subtypes, such as LBC‐Nonmucinous (Lung Bronchioloalveolar Carcinoma Non‐mucinous), solid predominant adenocarcinoma and adenocarcinoma with mixed subtypes." (PMID 37985446, 2023).
blood cancers (2 papers, 2024 to 2025). "Notably, chemotherapy that targets TOP2 enzymes, such as TOP2A, is often used to treat both solid tumors and blood cancers." (PMID 38895552, 2024).
benign tumors (1 paper, 2008). "Within 17q, the genes topoisomerase II-α (TOP2A), ets variant gene 4 (E1A enhancer binding protein, E1AF) (ETV4) and baculoviral IAP repeat-containing 5 (survivin) (BIRC5) showed increased expression in all samples compared to two benign tumors." (PMID 18522746, 2008). "TOP2A, ETV4 and BIRC5 showed increased expression in all MPNST samples compared to the benign tumors, in most cases more than 20-fold, whereas HOXB7 showed approximately similar expression levels in the MPNSTs and the benign tumors." (PMID 18522746, 2008). "TOP2A, ETV4 and BIRC5 showed increased expression in all MPNST samples, in most cases more than 20-fold, whereas HOXB7 showed approximately similar expression levels in the MPNSTs and the benign tumors." (PMID 18522746, 2008).
CNS tumors (1 paper, 2024). "The most commonly overexpressed genes in CNS tumors included TOP2A (67%), BIRC5 (59%), CDK4 (50%), BRIP1 (49%), NOTCH1 (41%), SMO (39%), and TP73 (39%)." (PMID 38347552, 2024).
hematologic cancers (1 paper, 2025). "Several clinically active agents targeting TOP2A, such as etoposide, doxorubicin, and mitoxantrone, have shown promise as a therapy for solid tumors and hematologic cancers." (PMID 41301416, 2025).
infectious disease (1 paper, 2025). A disorder directly resulting from the presence and activity of a microbial, viral, or parasitic agent in humans. "TOP2A is associated with infectious diseases, cellular responses to starvation, and selenoamino acid metabolism." (PMID 40787634, 2025).
kidney disease (1 paper, 2022). "Among these four genes, NCAPG, NUP93, and TOP2A were previously reported to be closely related to kidney disease, such as ccRCC." (PMID 35211510, 2022). "Among these four genes, NCAPG, NUP93, and TOP2A, were previously reported to be closely related to kidney disease." (PMID 35211510, 2022).
urological diseases (1 paper, 2025). "CD24, TOP2A, IQGAP3, UBE2C, and CRH mRNA levels were also significantly higher in patients with NMIBC than in those with hematuria, which may indicate that they could be used as discriminative biomarkers for BCa detection compared to urological diseases." (PMID 40282460, 2025).
TOP2A also shares sentences with these, for which no sentence is quoted: bacterial infections (15 papers); tuberculosis (9); gonorrhea (4); lung squamous cell carcinoma (4); gastric adenocarcinoma (3); heart failure (3); hematological malignancies (3); invasive ductal carcinoma (3); leprosy (3); oligodendroglioma (3); brain cancer (2); cholera (2); diffuse large B-cell lymphoma (2); fibrosarcoma (2); Huntington disease (2); kidney (2); liver cirrhosis (2); malaria (2); meningococcal disease (2); mesothelioma (2); papillary thyroid cancer (2); serous ovarian cancer (2); stomach cancer (2); testicular germ cell tumor (2); thymoma (2); uterine carcinosarcoma (2); abortion (1); acute lymphoblastic leukaemias (1); acute myocardial infarction (1); adenovirus infection (1).
A further 80 diseases each share a sentence with TOP2A in 1 paper.